MIR577 (microRNA 577)
Synonyms: hsa-mir-577; MIRN577; mir-577
Gene: MicroRNA gene on chromosome 4 (114,656,759 to 114,656,854, forward strand). Ensembl gene ENSG00000207931.
Gene Ontology:
Biological process: miRNA-mediated post-transcriptional gene silencing
Cellular component: RISC complex
Homologues: Orthologues: chimpanzee ptr-mir-577 (100% identical), macaque mml-mir-577 (96% identical).
Diseases named in the same sentence as MIR577 in open-access papers:
MIR577 is named in the same sentence as 3 diseases in open-access papers, as found by Europe PMC text mining. Sharing a sentence is not in itself a finding about the gene and the disease. The quoted sentences say what the papers report.
glioma (1 paper, 2021). A benign or malignant brain and spinal cord tumor that arises from glial cells (astrocytes, oligodendrocytes, ependymal cells). "Finally, MIR577 and MIR429 were previously reported to act as tumor suppressors in gliomas, while we have found them to function as oncogenes in the global setting of CNS tumors." (PMID 34204289, 2021).
MIR577 also shares sentences with these, for which no sentence is quoted: CNS tumors (1 paper); tumor (1).